ENSG00000268614 (novel transcript)
Gene: Protein-coding gene on chromosome 19 (7,533,595 to 7,540,059, forward strand). Ensembl gene ENSG00000268614.
Genetic constraint (gnomAD): Missense variants: 44 observed, 47.15 expected, observed/expected ratio (o/e) 0.93, 90% interval 0.73 to 1.2. Synonymous variants: 15 observed, 18.61 expected, observed/expected ratio (o/e) 0.81, 90% interval 0.54 to 1.24.